IL4 (interleukin 4)
Diseases named in the same sentence as IL4 in open-access papers (continued):
Sharing a sentence is not in itself a finding about the gene and the disease.
infection (continued). "In contrast, IL-4, which was reduced in the serum of P+ participants after infection, has been shown to inhibit neutrophil influx, and the balance between these cytokines may be important in regulating neutrophil activity during S. pyogenes infection." (PMID 35140232, 2022). "In our own experiments, by the analyses of cytokine genes in draining LN of C57BL/6 mice infected with different strains of L. major, we also noticed the higher expressions of both Ifng mRNA and Il12 mRNA and the lower levels of Il4 and Il10 expressions at five and eight weeks post infection." (PMID 35090305, 2022). "The decreased worm burden in Btn2a2-/- mice may be the result of an amplified local type-2 immune response at the site of infection, shown by increased frequencies of IL-4+ Th2 cells in the small intestine of Hp-infected Btn2a2-/- mice." (PMID 35145516, 2022). "We tested the serum samples for classical inflammatory and anti-inflammatory cytokines as systemic markers for a prolonged immune response, and observed a trend for slightly elevated cytokine levels for IL8, TNFα, IL6, IL12p70, IL10, IL5 and IL4 in the first four months after the infection." (PMID 36293090, 2022). "Next, we evaluated the immune response associated with the immunization by analyzing the expression of major proinflammatory (IFN-γ) and disease promoting (IL-10 and IL-4) cytokines in the splenocytes of LmexCen−/− and LmexWT injected hamsters at 11 weeks post-infection." (PMID 36463228, 2022). "Administration of rWnt5A prior to infection was also found to correlate with slightly lower plasma levels of IL-4, which may act together with IL-10 to aggravate disease pathogenesis." (PMID 35197983, 2022). "Some potential methods to achieve this that could be explored are by inhibiting or supplementing IFN-γ and IL-4 at the appropriate points in infection." (PMID 36159650, 2022). "Especially elevated IL‐4 titers, effective even at low concentrations, may promote atopic sensitization after infection, that could be thwarted by IL‐13 expression." (PMID 36271745, 2022). "Furthermore, the production of the cytokines IL-17A and IL-4, originating mainly from innate immune cells, seems to be important for controlling the larval lung burden at the beginning of the infection." (PMID 35844540, 2022). "We assume that the IL-4/IL-13 stimulation induced initial alterations in the skin samples that sufficiently alter the integrity of cell-cell junctions that allow the virus to reach its receptors and initiate infection." (PMID 35969080, 2022). "For instance, increased periodontal pathogen abundance will enhance the stimulation of TLRs, induce Th1 to secrete IL-2, IFN-γ, TNF-α to kill intracellular infection pathogens, and then induce Th2 to secrete IL-4, IL-5, IL-6, IL-13 to regulate humoral immunity and limit Th1 response." (PMID 35254118, 2022). "During infection in Merino sheep, the Th2 polarisation occurs around 9 days post-infection in the hepatic lymph nodes and 18 days post-infection in the liver, with a significant increase in IL-4 expression that suppresses IFNγ levels." (PMID 34207215, 2021). "Since we have shown that IL-4 signalling regulation occurs predominantly on naïve T cells, it may indicate that the early IL-4 environment during infection/vaccination may have significant implications in determining T cell fate." (PMID 34006897, 2021). "IFN-γ alone cannot fight infection and requires IL-2, IL-4, and GM-CSF to act synergistically." (PMID 34938794, 2021). "However, in case of IL4-/- mice, the load was observed between 10 to 20 dpi and there was a considerable reduction between 30 to 40 dpi and the infection was totally cleared by 40 dpi." (PMID 34226412, 2021). "Therefore, the increase in the IL-4 level after crocin treatment was an important indicator of the therapeutic efficacy of crocin in AE-infected BALB/c mice at an advanced stage of infection." (PMID 34256821, 2021).
infection (continued). "Type-I T cells produced type-I cytokines, such as IL-2, TNF-α, and IFN-γ, to enhance cellular response to remove infected cells, whereas Type-II T cells produced type II cytokines, such as IL-4, IL-5, and IL-10, to increase antibodies to attack exogenous antigen to prevent host-cell infection." (PMID 34200327, 2021). "It is very interesting that cell proliferation of BALB/c MSCs was decreased even after infection with the empty control lentiviral vector and IL-4 secreting lentiviral vector, but C57BL/6 MSCs showed increased proliferation after single infection with these two vectors." (PMID 33413614, 2021). "In particular, it will be important to assess whether separate or combined vaccination against IL-4 and IL-13 has any effect in models of infection with helminths." (PMID 33976140, 2021). "The treatment of infection was associated with a decrease in Treg level and a switch in their phenotype, namely, a decreased expression of ICOS and of naïve Treg and a systemic IL-6 and IL-4 inflammatory response." (PMID 34111180, 2021). "For example, besides infections with helminths or trypanosomes, other infections that affect thymic IL-4 levels might also impact TAIM differentiation." (PMID 34398252, 2021). "In conclusion, both the Type 1 hypersensitivity response, as suggested by IL-4 expression plus the defective Type 4 hypersensitivity response abrogated by IL-10 contribute to increased infection severity and compromise the development of an effective immune response." (PMID 34035796, 2021). "However, in the S. Gallinarum group, downregulation of expression of both the cytokines (IL-4 and IL-10) mRNA was evident at 6 h post-infection in comparison to mock-treated cells." (PMID 34446765, 2021). "Moreover, infected B6.vFLIP mice were more resistant to infection than WT mice in an IL-4-dependent fashion." (PMID 34249011, 2021). "Furthermore, substantially higher amounts of IFNγ and IL-4 were produced in the splenocyte supernatants of rAd5-YFV vaccine-immunized mice than those from rAd5-LcrV vaccinated animals in response to an infection." (PMID 33514747, 2021). "However, they either significantly subsided (IL-4 and IL-5) or maintained at a similar level (IL-13) in immunized mice in response to an infection with CO92." (PMID 33514747, 2021). "It has been reported that macrophages can produce IL-4 in response to infection." (PMID 34682248, 2021). "Meanwhile, despite the characteristics of permissiveness to infection, the macrophages activated by IL-4/IL-13 are also responsible for recruiting fibroblasts, keratinocytes, endothelial, and stem cells to wounds, which are fundamental to tissue repair and wound healing." (PMID 34660334, 2021). "Associations with infection were replicated at two SNP (IL13 rs1800925; IL4 rs2243250), and both of these SNP and also the IL10 (−1082/−819/−592) haplotype were also found to be associated with pathology, despite the studies using different phenotypes and in one case different parasite species." (PMID 33659002, 2021). "Although IL4 expression is also associated with IgE levels, the rs2243250 SNP is not, so its impact on intensity of infection must be via some other mechanism." (PMID 33659002, 2021). "Earlier, it was reported that the infection of Chlamydia leads to rapid production of IL-4/ IL-13." (PMID 34226412, 2021). "IL-4 is an important cytokine benefiting liver flukes that contributes to the inhibition of the host Th1-type pro-inflammatory response and is essential for the parasites to achieve immune evasion during the early stage of infection." (PMID 35071045, 2021). "The IL-4 signaling pathway also influences the infection-induced AHR and increases AAD severity." (PMID 34226412, 2021). "On the contrary, post–lung-stage infection increased IL-4 and IL-5 secretion." (PMID 34169075, 2021).
infection (continued). "In murine leishmaniasis, IFN- γ and IL-4 are produced reciprocally in resolving or progressive infection, supporting the hypothesis that distinct T-helper subsets moderate the spectrum of this infectious disease." (PMID 35126456, 2021). "The mRNA of IL-4 on the 24th day after infection, IL-8 on the 24th and 40th days, and IL-12p40 on the 40th day were significantly up-regulated; IL-6 mRNA was up-regulated during the test period, while IL-10 mRNA was significantly down-regulated on the 3rd and 31st days after infection." (PMID 34988138, 2021). "Nevertheless, whereas Th1 and Th2 cytokines correlate well with resistance and susceptibility to infection in certain experimental Leishmania models, some observations do not fit well with this paradigm and the role of IL-4 is particularly controversial." (PMID 34249011, 2021). "Furthermore, the IL-4 signaling pathway also influences infection-induced AHR and aids in increasing AAD severity." (PMID 34226412, 2021). "Underexpression of Th2 cytokines, such as IL4/IL13, as well as IL10 and TGFβ, which are primarily associated with tissue repair and extracellular matrix composition, was observed during the late stage of infection, especially in infected fish at 11°C." (PMID 32695119, 2020). "In our system, IL-4 can induce proliferation of uninfected cells, especially if they have been conditioned in the environment of the infected spleen, but the effect is blocked by intracellular infection." (PMID 33180876, 2020). "It is generally accepted that Th1 cells produce interferon-γ (IFN-γ), which promotes cell-mediated immunity, whereas Th2 cells may control infections from extracellular pathogens with the presence of (mainly) IL-4 and IL-13." (PMID 32326041, 2020). "Similarly, the concentrations of both IL-4 and IL-10 increased during infection and decreased after co-treatment with Alb and Sch B." (PMID 32635653, 2020). "Since TB-PE have, if any, very few mycobacterial load, we consider that the impact of potential in situ infection on the macrophage metabolic state, which may then lead M(IL-4) cells to become FM, might be very low." (PMID 33002063, 2020). "Notably, especially in splenocytes, IL-4/13 gene expression was significantly upregulated in all treatment groups while IFN-γ was only significantly upregulated after infection of unvaccinated fish." (PMID 33276596, 2020). "In general, although the levels of murine anti-inflammatory IL-4 and IL-10 cytokines were low in all groups before infection, examination of the IFN-γ/IL-10 ratios showed that the values were higher following ChimeraT/saponin immunization when compared to the individual proteins." (PMID 32821440, 2020). "In sOP subjects, a significant dependency of IL-4 expression on the frequency with which these children experienced viral URI was observed, such that sOP samples were likely to have higher IL4 levels at low frequencies of viral URI infection (discussed further below)." (PMID 32595639, 2020). "Because IL-4 plays a crucial role in VL susceptibility and progression and is involved in the regulation of IFN-γ production, its absence has a positive effect on the progression from subclinical disease to spontaneously resolved infection." (PMID 32966326, 2020). "In addition, IL-4 from basophils and eosinophils also promotes type-2 inflammation at the site of infection/colonization." (PMID 32793230, 2020). "After infection with LVS, six cytokines were significantly higher in wild-type BMDM cultures with immune vs. naïve splenocytes, whereas in cultures with GBP-deficient BMDM IL-2 and IL-3 were higher and IL-4 lower with immune vs. naïve splenocytes." (PMID 33363054, 2020). "In addition, in children with submicroscopic infections, IL-12p70 correlated negatively with IL-10 (r = -0.52, p = 0.012), whereas, granzyme B correlated positively with IL-4 (r = 0.62, p = 0.002)." (PMID 33281757, 2020).
infection (continued). "In addition, IL-4 levels were lower than in healthy animals at 45 dpi, except for the high-dose infection group, which was decreased at 30 dpi." (PMID 32085808, 2020). "However, the expression of IL-4 and IL-5 is increased due to infection in the taiep groups (p < 0.05)." (PMID 32817660, 2020). "However, IL-4 neutralization during infection of pregnant mice did affect congenital transmission to offspring." (PMID 32429367, 2020). "Similarly, for G. strigosum, simulations capture well the mean trend of infection and immune responses over time although there is a tendency for an underestimation of parasite intensity and IL4 around 45-60 days post infection." (PMID 33226981, 2020). "As the infection progresses, the immune response, modulated in part by IL-10, shifts to a mixed Th1/Th2 profile and then to a Th2 profile by 6 dpi with a significant increase of IL-4, IL-5 and IL-13 levels." (PMID 33023672, 2020). "However, we do note that the mean peak of infection is overestimated, and this coincides with the underestimation of IL4 mean values in the first 40 days post infection, despite the robustness of the estimations and small CIs." (PMID 33226981, 2020). "Mice lacking ILC2s due to conditional deficiency of the transcription factor RAR-related orphan receptor alpha (Rora) displayed a massive downregulation of features of type 2 immunity as reflected by reduced levels of the type 2 signature cytokines IL-4, IL-5, and IL-13 at 14 days post-infection." (PMID 32117319, 2020). "However, in the context of N. brasiliensis infection, iILC2s make IL-4 in addition to IL-13 at 5 days post-infection." (PMID 32793230, 2020). "With the development of infection, Th1 immune response could shift to Th2, following the overexpression of IL-4." (PMID 32066378, 2020). "Thus, during clearance of infection, the increase in IL-4 maintains goblet cell function and protects it against the increasing levels of TNF-α and IFN-γ." (PMID 30665337, 2019). "Additionally, T. canis-infection led to a prominent increase of anti-inflammatory IL-4 and IL-5 in the acute/subacute phase of infection which reached homeostatic levels with beginning of the chronic phase (day 42 pi)." (PMID 31315623, 2019). "Thus, during clearance of infection, the concomitant increase in IL-4 protects and maintains goblet cell function against the increasing levels of TNF-α and IFN-γ." (PMID 30665337, 2019). "Here, the levels of IL-4, IL-6, and IL-22 showed a similar trend during the infection period, indicating they might help to balance inflammatory reactions." (PMID 31711531, 2019). "In addition, the middle ear fluid of the Junbo mouse has consistently high levels of IL-4 during NTHi infection." (PMID 31548315, 2019). "To verify that the effect observed in murine pmacs was not impacted by the lack of type 1 interferon signaling, we performed a similar experiment in WT pmacs and found that IL-4/IL-13 treatment increased infection 2.5-fold, consistent with the effect observed in Ifnar-/- cells." (PMID 31825972, 2019). "Th2-like cytokines, such as IL-4 and IL-6, decayed 1 year after the infection." (PMID 30936869, 2019). "Similarly, a downregulation of the immune response, albeit not always significant, was found in the dual compared to the single infection; significant variables to note were IL4 and Tbet." (PMID 31871660, 2019). "Thus, we stimulated the cultures with IL-4 after infection and repeated the experiments of intracellular amastigote count." (PMID 31856207, 2019). "There is evidence that IL-4 and other Th2 cytokines play protective roles in re-infection than in primary infections, IL-4 knockout mice demonstrated optimal control of primary infection with P. chabaudi chabaudi, but had a more exacerbated disease upon reinfection." (PMID 31856836, 2019).
infection (continued). "In addition to enhancing mucin production and transport, IL-4 also had a protective effect on the integrity of the in vitro mucosal surface, goblet cell number, and the amount of mucin produced during infection." (PMID 30665337, 2019). "This is consistent with data described in LCL lesions due to L. guyanensis, in which a Th2 response (IL-4 and/or IL-13) transiently predominates during the early phase of infection, followed by the development of a Th1 (IFN-γ) response during the late course of lesion development." (PMID 30810524, 2019). "Taken together, we show in a mouse TB model that infection with highly virulent clinical Beijing- and EAI-strains is associated with influx of B-cells and elevated IL-4 levels in the lungs, while less virulent H37Rv bacteria induce T-cell influx and higher IFN-γ and IL-17a levels at peak infection." (PMID 31882653, 2019). "Pmacs exposed to IL-4/IL-13 were more susceptible to VLP fusion, demonstrating that enhanced entry, likely secondary to enhanced binding, is at least in part responsible for the increased infection observed in M2 macrophages." (PMID 31825972, 2019). "In total, these studies demonstrate that IL-4/IL-13 polarization of macrophages generates a macrophage that is highly susceptible for EBOV entry and infection through enhancement of cell surface CLRs, and further highlight the importance of macrophages in the pathogenesis of EBOV." (PMID 31825972, 2019). "IL-4 and IL-13 increased the production further in the presence of infection (p < 0.05)." (PMID 30665337, 2019). "Indeed, the authors found limited evidence that proliferative expansion in general, let alone driven by IL‐4, contributes to the number of macrophages present in the liver at any stage during the infection." (PMID 31267552, 2019). "Examination of RNA expression of known surface receptors that bind and internalize filoviruses demonstrated that IL-4/IL-13 stimulated expression of the C-type lectin receptor DC-SIGN in human macrophages and addition of the competitive inhibitor mannan abrogated IL-4/IL-13 enhanced infection." (PMID 31825972, 2019). "There was also a decrease in IL-4, IL-6, IL-10, and IL-13 in the late stages of infection." (PMID 31192210, 2019). "Even though IL-4 and IL-13 may have similar effects on immune cells, both cytokines are differentially regulated in mice during an infection with the rodent hookworm Nippostrongylus brasiliensis as well as in the present study." (PMID 31315623, 2019). "IL-4 functions to enhance IFN-γ production in the late stage of infection." (PMID 30894865, 2019). "We also analyzed the effect of cellular differentiation on IFI16 expression following infection in mature dendritic cells derived by treating ex vivo CD14+ monocytes with granulocyte-macrophage colony-stimulating factor (GM-CSF)/interleukin-4 (IL-4)/lipopolysaccharide (LPS)." (PMID 31796538, 2019). "Infection of both resting and IL-4 activated macrophages induced the production of IL-10, thus raising the possibility that this cytokine acts in an autocrine manner to maintain the alternative activation phenotype, or induces it in the case of resting macrophages." (PMID 31134002, 2019). "Other studies analyzing the transcription of this cytokine after infection by the closely related protozoan, N. caninum, found an increase in IL4 levels in the placenta from sheep and cattle and even mice, confirming that this cytokine plays a key role in the pathogenesis of neosporosis." (PMID 31533826, 2019). "Interestingly, in contrast to the reduction in IL-4, IL-9 and IL-13 cytokine release later in infection, we saw a stronger, secondary peak of TGFβ at day 12 p.i.." (PMID 30998782, 2019). "Indeed during a schitosome infection, Th1/Th2 dichotomy that occurs is attributed to the Th2 immune response (especially the production of IL-4), IL-10 and T regulatory (Tregs) cells response." (PMID 31449535, 2019).